ASCL1 (achaete-scute family bHLH transcription factor 1)
Diseases named in the same sentence as ASCL1 in open-access papers (continued):
Sharing a sentence is not in itself a finding about the gene and the disease.
tumor (continued). "From the CRC network, only ASCL1 emerged from this analysis, given its different dynamic expression during murine TH-MYCN-driven tumor formation compared to HAND2, PHOX2B, GATA3 and ISL1." (PMID 34638267, 2021). "ASCL1 is also known as a repressive target of Smad TFs downstream of transforming growth factor‐β (TGF‐β) and is required for tumor formation by suppressing apoptosis in SCLC cells." (PMID 31782890, 2020). "We found that achaete-scute homologue 1 (ASCL1), a main driver of SCLC, was increased nearly 50-fold in tumour tissues compared to matched normal specimens." (PMID 32499571, 2020). "Nevertheless, overlap analysis identified well-established NE-associated genes such as DLL3 and its upstream regulator, achaete-scute complex-like 1 gene (ASCL1), as having distal ATAC-seq peaks and overlapping a tumor DMR in bulk tissue analysis." (PMID 32707835, 2020). "High magnifications revealed that ASCL1, OLIG2, and SOX2 are also expressed specifically within the YFP+ tumor cells, which are highly irregular in shape, morphology, and density compared to normal YFP+ cells on the nontumor side (not shown)." (PMID 32573857, 2020). "Based on our results in Drosophila, we predict that introducing ASCL1 would override the repressive effect of TLX, induce neuronal differentiation and reduce tumour growth, thereby providing an effective treatment." (PMID 32073402, 2020). "In GEMM mouse models of SCLC, it was found that ASCL1 is present in mouse pulmonary NE cells, and is required for SCLC tumor formation." (PMID 31324758, 2019). "The regulators of transcription and differentiation, ASCL1 and DLL1 in the Notch signalling pathway, were found to be up-regulated in the mtDNA-depleted tumours but down-regulated in the cells." (PMID 30208958, 2018). "In general, epithelial cell lines and tumors were associated with cancer stem cell markers (CD24, ALDH1A1, and PROM1), markers of tumor aggressiveness (MYCL1 and ASCL1), and markers of apoptosis (BCL2 and BCL2L11)." (PMID 28212573, 2017). "Levels of NE cancer markers, which include aschaete-scute homolog 1 (ASCL1), synaptophysin (SYN), and chromogranin A (CgA), correlates with tumor burden." (PMID 29050323, 2017). "Of these, nine tumours displayed low ASCL1/high DKK1 and six tumours high ASCL1/low DKK1 expression." (PMID 19744316, 2009). "This framework reveals both canonical and previously unrecognized lineage-restricted dependencies within highly plastic tumor and NEPC states, including a therapeutically targetable dependency on the aryl hydrocarbon receptor (AHR) in a novel hybrid stem-like/ASCL1 population." (PMID 42146571, 2026). "To obtain a more definitive result, we also performed ATAC-seq analysis on an ASCL1+ PDX tumor that was homogeneously negative for FOXA2, in comparison to 3 ASCL1+/FOXA2+ PDX tumors." (PMID 40419484, 2025). "The ROR2–ASCL1 axis is validated as a molecular circuit where therapeutic pressure suppresses AR signaling, leading to ROR2 induction and downstream ASCL1-mediated reprogramming of the tumor lineage." (PMID 41470892, 2025). "Once PRAD tumor cells lose contact with ECM (by experimental withdrawal in organoid culture or stochastically during in vivo tumor expansion), YAP/TEAD activity is acutely switched off, followed by induction of ASCL1 and an eventual transition to NEPC." (PMID 41509338, 2025). "Given the established role of immunomodulatory factors in shaping the tumor microenvironment and influencing immune responses, our findings of a negative correlation between ASCL1 levels and these factors suggest an immunosuppressive effect in BC." (PMID 39963143, 2025). "Both RPR2 and CRPR2 tumors consisted of NE (Ascl1 and Calca positive) and non-NE (Ascl1 and Calca negative) tumor cells." (PMID 41353272, 2025). "Additionally, we examined the potential roles of ASCL1 and CHD7 in tumor progression by comparing their expression levels in squamous cell carcinoma tumors versus adjacent non-cancerous tissues." (PMID 40332288, 2025).
tumor (continued). "Due to the ability of ASCL1 and OLIG2 to directly bind to the other’s loci and loci of cell cycle genes, we next investigated how alteration of the levels of ASCL1 and/or OLIG2 affect each other’s expression and tumor cell proliferation at both early and terminal stages of the various tumor types." (PMID 39609428, 2024). "Similarly, our study concerning the analysis of our scRNA-seq in metastatic SCLC also identified the different ASCL1 and NEUROD1 expression patterns, which further uncovered the diversity of inter-patient and intra-tumor heterogeneity." (PMID 39103941, 2024). "Loss- and gain-of-function combined with scRNA-seq reveal that tumor cells with higher levels of ASCL1 relative to OLIG2, as seen in the Olig2-CKO and Ascl1-OE tumors, favor activation of a NSC/astrocyte program, characterized by high expression of GFAP and a highly migratory or diffuse phenotype." (PMID 39609428, 2024). "In contrast, dCKO showed no incorporation of EdU within tdTOM+ cells at P30 or even in the few terminal-stage dCKO tumors, indicating that tumor cell proliferation was significantly compromised in the absence of both ASCL1 and OLIG2." (PMID 39609428, 2024). "Unlike the transition phase, Ascl1 extinction within established NEPC resulted in transient tumor regressions followed by ASCL1− NEPC progression, underscoring the importance of early pharmacological intervention to prevent plasticity." (PMID 39394434, 2024). "Recent studies demonstrated that MYC activates Notch signaling, driving the temporal evolution of SCLC heterogeneity by conducting the sequential conversion of SCLC tumor cells from an ASCL1- to a NEUROD1- and, ultimately, to a non-NE (YAP1) state." (PMID 38395864, 2024). "ASCL1 and OLIG2 dynamically interact, affecting tumour cell types, migration, and proliferation." (PMID 39457550, 2024). "While TKO tumor cells were primarily NE (ASCL1+), TKO-Nicd1 organoid tumor cells were non-NE and expressed markers of prostate epithelium (Krt5+, Krt8+, Hes1+)." (PMID 39024561, 2024). "Similar to Ascl1-CKO, Olig2-CKO resulted in 100% tumor formation with a median survival of 92 days." (PMID 39609428, 2024). "The research also showed that ASCL1, which had a positive correlation with SLC6A13, controls the production of this protein and suppresses the growth, migration, and invasion of HCC cells, hence functioning as a tumor suppressor." (PMID 38780447, 2024). "The purpose of this research was to clarify the function of achaete-scute family bHLH transcription factor 1 (ASCL1) and solute carrier family 6 member 13 (SLC6A13) in influencing tumor cell behavior, inflammatory responses, and the regulation of inflammasomes." (PMID 38780447, 2024). "The fact that ASCL1 and OLIG2 can physically and genetically interact suggests that OLIG2 may directly repress ASCL1’s ability to promote tumor migration through these interactions." (PMID 39609428, 2024). "IHC analysis revealed divergent ASCL1 and NEUROD1 expression in discrete tumor foci." (PMID 38645034, 2024). "Based on their developmental roles in glial cell fate specification, we hypothesized that altering the levels of ASCL1 and/or OLIG2 should influence the cell or tumor types of the GBM mouse model." (PMID 39609428, 2024). "This was revealed by ASCL1’s ability to promote an increase in early migration of newly transformed GFP+ tumor cells out of the SVZ at P4 into the striatum, corpus callosum, and cortical plate of Ascl1-OE mice prior to their specification into either GFAP+ or SOX10+ tumor cells." (PMID 39609428, 2024). "Indeed, the key transcriptional regulator of the SCLC-A subtype, ASCL1, upregulates expression of SOX2, and this is important in both tumor establishment and MYC-dependent subtype regulation." (PMID 39456533, 2024).
tumor (continued). "Taken together, our findings imply that ASCL1 and OLIG2 function redundantly downstream of TNP-deletion to transform affected radial glia into proliferating tumor cells, but these transcription factors seem to regulate opposing aspects of tumor cell migration in the brain." (PMID 39609428, 2024). "Further multivariate analysis controlling for tumor pathological stages confirmed the independent predictive value of ASCL1 and VIM but not POU2F3 for ACT benefit." (PMID 37789961, 2023). "This subtype exhibits the highest levels of immune cell infiltration into the tumor, and is identified by a mesenchymal phenotype and a non-neuroendocrine profile with low or absent expression of ASCL1 and NEUROD1." (PMID 38203275, 2023). "Nevertheless, a similar (yet statistically not significant) tendency was observed in the case of ASCL1 expression and tumor stage as in the WTS cohort." (PMID 35489038, 2022). "Both ASCL1 and NEUROD1 were expressed in the nuclei of tumor cells." (PMID 35220975, 2022). "Furthermore, treatment of iBAP-II represses neuroendocrine lineage-specific ASCL1/MYCL/E2F signaling in SCLC cell lines, and dramatically inhibits SCLC cell viability and tumor growth in vivo." (PMID 35194152, 2022). "Consistent with our data above, ZFP36L1 was expressed in the inflammatory tumor cell subpopulation that emerged after cisplatin recurrence while its expression was largely absent in the ASCL1/INSM1-high neuroendocrine populations." (PMID 36008402, 2022). "All genes were up-modulated in mixed cases irrespective of the tumor location, except for ASCL1 that was not modulated in mixed cases of the gastrointestinal tract." (PMID 35608806, 2022). "The SCLC-P tumor, with no detectable expression of ASCL1 and NEUROD1, consisted of individual cells expressing heterogeneous levels of POU2F3, with half of the cells having no detectable expression of POU2F3." (PMID 36195615, 2022). "In accordance with the RNA-seq, the tSNE analysis showed a single cluster of the FLM5 tumor cells with accessibility at ASCL1 promoter but not at NEUROD1." (PMID 34599169, 2021). "Notably, this was not only seen in ASCL1+ tumors (for example, SCLC-04, NE score 0.4) but also in the POU2F3+ tumor with a positive NE-score (SCLC-15, NE score 0.26)." (PMID 33750914, 2021). "Similar to our findings for ASCL1, tumor formation persisted in the absence of each of these transcription factors." (PMID 32573857, 2020). "To test the functional roles of ASCL1 and SOX11 in DIPG tumor cells, we used CRISPR/Cas9-mediated gene editing to inactivate them individually and in combination in ACVR1 mutant (SU-DIPG-IV, SU-DIPG-XXI, SU-DIPG-XXXVI, HSJD-DIPG-007) or wild-type (SU-DIPG-VI) cells." (PMID 32142668, 2020). "As illustrated for a GlastCreERT2;Ascl1GFP/F;Nf1F/F;Tp53F/F mouse, GFP driven by the endogenous Ascl1 locus marks precisely the tumor cells but ASCL1 was no longer detected." (PMID 32573857, 2020). "Together, these findings demonstrate that glial transcription factors and the OPC‐like identity of the tumor cells are still retained in the absence of ASCL1." (PMID 32573857, 2020). "Very interestingly, ASCL1-silenced CSCs gave rise to tumors that, while not showing differences in tumor growth, were morphologically pleomorphic and displayed MES features." (PMID 30538287, 2019). "Players within the ASCL1 axis could also be used as key molecular markers to indicate NE physiology and the vulnerability of CRPC tumours to developing into NEPC." (PMID 31836808, 2019). "ASCL1 and NEUROD1 expression in SCLCs help to define tumor heterogeneity." (PMID 30060526, 2018). "Furthermore, the elevated expression of ASCL1 and LMO4 seen in the MYCN-overexpressing SY5Y-MYCN cells matched the high expression of these genes in the poor outcome tumours." (PMID 28187790, 2017). "ASCL1 and NEUROD1 are both necessary for SCLC tumor survival and disease progression, but regulate different downstream pathways, and whether they are involved in EMT is unknown." (PMID 28212573, 2017).
tumor (continued). "We have recently reported that ASCL1 is invariably expressed in PETs, and suggested that the observed lack of nuclear HES1 might contribute to the expression of ASCL1 in these tumours." (PMID 19744316, 2009). "Nine tumours displayed low ASCL1/high DKK1 and six tumours high ASCL1/low DKK1 expression." (PMID 19744316, 2009). "ASCL1 is targeted by NOTCH signaling and research suggested that one inactivating NOTCH mutation was sufficient to induce neuroendocrine differentiation from nonneuroendocrine tumor cells or tumor precursors." (PMID 40040728, 2025). "To further confirm the prognosis of these findings, we performed co‐staining for pan‐cytokeratin, ASCL1, and KRT6A on clinical tumour samples from treatment‐naïve KRASG12C‐mutant LUAD, confirming the presence of two distinct subpopulations within individual tumours." (PMID 41025426, 2025). "Furthermore, ASCL1 and OLIG2 function redundantly to promote tumor formation and proliferation." (PMID 39609428, 2024). "Notably, ASCL1 and OLIG2 sit at the apex of the GBM cellular hierarchy, where their dynamic co-expression and functional interactions are directly responsible for determining NSC/astrocyte-like and OPC-like tumor cells, respectively." (PMID 39609428, 2024). "However, the functional impact of ASCL1’s function in the context of GBM extends beyond just cell type/subtype commitment and tumor cell proliferation but also to produce highly migratory and diffuse tumor cells." (PMID 39609428, 2024). "Interestingly, neither Ascl1-CKO nor Olig2-CKO had a significant impact on tumor cell proliferation at P30 or terminal stages." (PMID 39609428, 2024). "In addition, neither the SC53 tumor cells nor its ASCL1+ subpopulation showed a strong correlation between A2 scores and M scores." (PMID 36900269, 2023). "In addition, ASCL1/NEUROD1 double-negative tumours (14% SCLC) are a distinct subtype of SCLC characterized by low expression of neuroendocrine markers." (PMID 37870696, 2023). "Meanwhile, in another study, the same group also showed that the expression of conventional markers linked with NE differentiation is substantially higher in ASCL1‐ and NEUROD1‐defined tumours (vs. ASCL1/NEUROD1‐double‐negative tumours), which as well corresponds with our findings." (PMID 36149789, 2022). "On univariate analyses, longer overall survival was also associated with older age (> 3 years) and positive ASCL1 staining, but not OLIG2 or GFAP staining, tumor location, gross total resection or the presence of pathogenic/likely pathogenic SMARCB1 germline variants." (PMID 35501487, 2022). "ASCL1 function is an upstream regulator of the Ret Proto-Oncogene, so combined with our findings, we speculate that in GBM, ASCL1 may mediate RET activation through EGFR, thereby affecting tumor progression." (PMID 36147490, 2022). "Moreover, MSK761c did not cluster with MSK761 in the PCA, but with the other ASCL1-driven samples, further demonstrating the heterogeneity of tumor cell characteristics found in this patient." (PMID 35440124, 2022). "Furthermore, the similarity in terms of the DNA accessibility shown by SCLC and NEPC depends on the status of ASCL1 or NEUROD1 expression but not on the tumor type." (PMID 34599169, 2021). "Finally, in agreement with our earlier finding that tumor cell proliferation is decreased in the absence of ASCL1, gene‐set‐enrichment analysis revealed that cell cycle related genes were highly enriched in the downregulated genes in the Ascl1CKO tumors." (PMID 32573857, 2020). "SCLC characterised by NE differentiation highly express transcriptional regulators ASCL1 and NEUROD1 and shows classic neuroendocrine morphology with in vitro cells growing in non-adherent tumour clusters." (PMID 39215193, 2024). "The median survival of Ascl1-OE tumor mice (72 days), though not different from control, was significantly shorter (p < 0.0001) compared to Ascl1-CKO and Olig2-CKO tumor mice." (PMID 39609428, 2024).
tumor (continued). "One case (1.96%) had an expression of both ASCL1 and POU2F3, but this expression was present in different regions of the tumor and did not overlap." (PMID 39682568, 2024). "Tumours that are predominantly positive for MYC are in either POU2F3 or YAP1 subgroups, while MYC negative tumours are mostly in ASCL1 and NEUROD1 subtypes." (PMID 37870696, 2023). "In vivo, although reduction of CELSR3 did not impact NEPC tumor growth rate or metastatic potential, we did find that reduction of CELSR3 resulted in a diminution of NEPC markers (e.g., SYP, ASCL1, INSM1, SYP, and CHGA) in vitro and in vivo." (PMID 37546702, 2023). "If we extend the marker genes to include the non-classical ones such as MUC1 for ADC, SOX2 for SCC, and ASCL1 for NET, the mixed-lineage cancer cells were notably observed in all of the sixteen patients from whom we isolated epithelial cells in tumor tissues." (PMID 35962452, 2022). "To investigate a potential LTF behavior of both TFs in NEPC, we performed SE analysis by H3K27ac profiling of ASCL1 and NEUROD1 NEPCs, and found that all models showed SE activation in common at a number of TFs (INSM1 and NFIB) regardless of the tumor subtype." (PMID 34599169, 2021). "PDGFRα was also highly coexpressed by the ASCL1+ and OLIG2+ (not shown) tumor cells, whereas GFAP and to a lesser extent S100β and NEUN, although found in some parts of the tumor, did not overlap significantly with SOX2 or ASCL1." (PMID 32573857, 2020). "O + /A + tumors showed solid-spindle features and diffuse GRP and frequent ACTH expression, trabecular patterns characterized ASCL1-negative tumors, while oncocytic histology predominated in OTP-negative tumors, highlighting their role in defining tumor heterogeneity." (PMID 41196447, 2025). "Our data revealed that ASCL1, NEUROD1, and POU2F3 were exclusively expressed in the malignant cells of SCLC tumors, however, YAP1 was mainly expressed in normal epithelial cells rather than tumor cells." (PMID 36195615, 2022). "Importantly, ASCL1 but not NEUROD1 directly regulates well-known SCLC-related oncogenes and is required for tumor formation in vivo of GEMMs." (PMID 30477547, 2018). "While ATOH1 CDXs expressed neither ASCL1 nor POU2F3, ATOH1 was expressed alone (CDX17P) or in combination with NEUROD1 at the transcript and protein levels (CDX25, 78% positive tumor cells; CDX30P, 78% positive tumor cells; CDX17, moderate NEUROD1 expression, 30% positive tumor cells)." (PMID 40305287, 2025). "Heatmap analysis of gene expression in adherent cells and stem‐like tumor spheres revealed a negative correlation between YY2 and stem‐related factors, including CD44, SOX9, SALL2, KLF15, OCT4 (also known as POU class 5 homeobox 1 or POU5F1), MYC, ASCL1, and POU3F2." (PMID 37300334, 2023). "Thus, unlike ASCL1, this suggests that OLIG2 may function as a suppressor of tumor cell migration." (PMID 39609428, 2024).